SIRT1 (sirtuin 1)
Diseases named in the same sentence as SIRT1 in open-access papers (continued):
Sharing a sentence is not in itself a finding about the gene and the disease.
liver cancer (continued). "Collectively, these findings highlight the novelty of the pivotal role of c-Myc and SIRT1 as molecular targets in cancer treatment, and how they are critically involved in Isoimperatorin-induced apoptosis in HCCs as potent molecular targets in liver cancer therapy." (PMID 38673833, 2024). "In addition, SIRT1 also has a certain influence on chemotherapy resistance in liver cancer." (PMID 35432540, 2022). "The inhibition of RPS3/SIRT1 pathway by 5-formylfuran-2-yl methyl 4-hydroxy-2-methylenebutanoate (FMHM) represses HCC progression suggesting that RPS3/SIRT1 could serve as a potential therapeutic target in liver cancer." (PMID 34873618, 2021). "Additionally, SIRT1-activated p38 increased liver cancer malignancy." (PMID 26824501, 2016). "The SIRT1/MRPS4 axis is involved in metabolic reprogramming, facilitates tumor progression in HCC and plays a critical role in maintaining the stemness of liver cancer stem cells (CSCs) and participating in tumor progression." (PMID 40713706, 2025). "In a liver cancer model induced by DEN exposure, AIF1+CSF1R+ MSCs exhibiting elevated expression of sirtuin 1 (SIRT1) was identified within liver tissues undergoing chronic inflammation prior to the onset of cancer." (PMID 40676710, 2025). "This highlights the metabolic role of SIRT1 in HCC pathogenesis and suggests its potential relevance for future liver cancer treatments." (PMID 40427612, 2025). "In liver cancer, lncRNA small nucleolar RNA host gene 7 (SNHG7) suppresses NLRP3-triggered pyroptosis through the miR-34a/SIRT1 pathway." (PMID 39267831, 2024). "Our findings indicated that SIRT1 and SOX2 were upregulated in human liver cancer tissue sections compared to the adjacent tissue." (PMID 35674129, 2022). "Silencing of SNHG7 lowered SIRT1 expression, but elevated the expression of NLRP3, caspase-1 and IL-β, eventually contributing to pyroptosis in liver cancer cells." (PMID 36387211, 2022). "SIRT1 is up-regulated in some cancers including acute and chronic myeloid leukemias (AML and CML) but down-regulated in breast and liver cancers." (PMID 36600891, 2022). "Therefore, SIRT1 may be a molecular target for liver cancer therapy." (PMID 35432540, 2022). "In liver cancer, NLRP3-related pyroptosis pathway suppressed by SNHG7 through regulation of miR-34a/SIRT1 ceRNA axis." (PMID 34488540, 2021). "SIRT1 is upregulated in HCC and promotes liver cancer by stimulating deactylation of the farnesoid X receptor to an extent that in turn dysregulates bile acid homeostasis." (PMID 33783990, 2021). "In liver cancers, SNHG7 worked as a ceRNA of miR-34a, and SIRT1 was proved to be a direct target of miR-34a." (PMID 34381023, 2021). "In line with previous reports, we confirmed higher expression of Sirt1 in human HCC samples and DEN-induced mice liver cancers compared to normal liver tissues." (PMID 33854041, 2021). "Therefore, HULC increases the cellular autophagy by increasing LC3II dependent on Sirt1.Noteworthy, excessive HULC reduces the expression of PTEN, β-catenin and enhances the expression of SAPK/JUNK, PKM2, CDK2, NOTCH1, C-Jun in liver cancer cells." (PMID 29895332, 2018). "In the present study, resveratrol significantly up-regulated the expression levels of SIRT1 mRNA in the human monocyte cell line THP-1 and the human liver cancer cell line HepG2, whereas the ARs did not affect the expression levels of SIRT1 mRNA." (PMID 28252007, 2017). "We therefore propose that SIRT1 may act as a common activator of both YAP and Wnt/β-catenin signaling during development of liver cancer." (PMID 26824501, 2016).
liver cancer (continued). "In addition, capsaicin can also affect the SIRT1/NOX4 signaling pathway by reducing the level of SIRT1 protein, increasing NOX4 protein levels and caspase-3/-7 activity, and promoting oxidation, apoptosis and DNA damage in liver cancer cells." (PMID 36278230, 2022). "Moreover, SIRT1 regulates the transcription of SOX2 through DNA methylation, leading to hypermethylation of the SOX2 promoter, which affects the self-renewal and tumorigenicity of liver cancer stem cells (CSCs), highlighting SIRT1’s vital role in cancer progression." (PMID 40052151, 2025).
non-alcoholic fatty liver disease (71 papers, 2014 to 2026). "Ovariectomy (OVX)-induced non-alcoholic fatty liver disease (NAFLD) has been linked to downregulation of the Erα/Sirt1/PGC-1β axis in liver tissue." (PMID 41471349, 2025). "The levels of SIRT1 are involved with the insulin sensitivity of cells and, therefore, associated with non-alcoholic fatty liver disease and DM." (PMID 34880765, 2021). "SIRT1 has previously been implicated in liver regeneration and in resolving hepatocyte lipid accumulation following NR treatment in the setting of nonalcoholic fatty liver disease." (PMID 33690226, 2021). "Recent studies have demonstrated that STS had potential to promote the SIRT1 expression, thereby providing relief for various diseases, including non-alcoholic fatty liver disease, chronic obstructive pulmonary disease, and cardiovascular disease." (PMID 40890747, 2025). "It is reported that the level of SIRT1 transcription is decreased in non-alcoholic fatty liver disease (NAFLD) patients compared with normal individuals." (PMID 40943413, 2025). "It has been found that moderate Strong-flavor Baijiu intake can attenuate mild ALD or non-alcoholic fatty liver disease (NAFLD) induced by ethanol intake in rats by through the glycerolipid pathway or the sirtuin-1/-adiponectin-dependent signal cascades." (PMID 40063641, 2025). "Further, SIRT1 regulates nonalcoholic fatty liver disease development via the NF-κB and AMPK pathways." (PMID 39372420, 2024). "In non-alcoholic fatty liver disease with iron overload, silencing of miR-34a can increase Sirtuin 1 expression and consequently alleviate TG accumulation." (PMID 39139452, 2024). "Sirt1 is also involved in cell cycle regulation, cell differentiation, cell survival, and apoptosis, with effects on nonalcoholic fatty liver disease, inflammation, energy metabolism, cognition, glucose/cholesterol metabolism, and amyloidosis." (PMID 37545895, 2023). "have used AAV8 to deliver the Sirt1 gene to the liver, resulting in long-term sustained expression of the Sirt1 gene and successfully preventing high-carbohydrate-diet-induced non-alcoholic fatty liver disease." (PMID 37663132, 2023). "MiR-222-3p has also recently been reported to target SIRT1 in cancer, arthritis and non-alcoholic fatty liver disease." (PMID 36979007, 2023). "At the hepatic level, SIRT1 activity acts as a protective factor in the context of glucose intolerance and non-alcoholic fatty liver disease (NAFLD)." (PMID 35409409, 2022). "Berbamine, a natural bisbenzyl-isoquinoline alkaloid, attenuates hepatic steatosis by activating the SIRT1/LKB1/AMPK signaling axis in high-fat diet (HFD)-induced non-alcoholic fatty liver disease (NAFLD) rats." (PMID 35628280, 2022). "Clinically, a dysregulated Sirt1 level and its activity have been found in the livers of patients with extrahepatic cholestasis and nonalcoholic fatty liver disease." (PMID 35624826, 2022). "Resveratrol and caloric restriction induced autophagy stimulated by the SIRT1-FoxO1 pathway has been identified as a critical protective mechanism of nonalcoholic fatty liver disease (NAFLD)." (PMID 36185335, 2022). "SIRT1 is phosphorylated by CK2 at Ser-164 and loses its deacetylase activity in obese mice, which is linked to the development of nonalcoholic fatty liver disease." (PMID 34443331, 2021). "Reduction of SIRT1 deacetylase activity increases HFD-induced non-alcoholic fatty liver disease (NALFD) development." (PMID 33806509, 2021). "LPS is a critical repressor of sirtuin 1, which was recently found to be involved in non-alcoholic fatty liver disease and various organ diseases." (PMID 34483936, 2021). "Of note, T2 has shown protection against intracellular damage in diabetic nephropathy and non-alcoholic fatty liver disease (NAFLD) in a SIRT1-dependent manner." (PMID 30360449, 2018). "Among seven mammalian sirtuins, sirtuin 1 (Sirt1) is the most extensively studied and plays a role in both alcoholic and nonalcoholic fatty liver diseases." (PMID 30055626, 2018).
non-alcoholic fatty liver disease (continued). "Previous studies have reported that Nampt mRNA is decreased in the liver of human subjects with non-alcoholic fatty liver disease, and Nampt has been shown to protect hepatocytes by increasing SIRT1 activity." (PMID 30423963, 2018). "This trial will first assess the effects of green cardamom (Elettaria cardamomum) on blood glucose indices, lipids, inflammatory factors, paraxonase-1, sirtuin-1 and irisin in overweight or obese patients with nonalcoholic fatty liver disease (NAFLD)." (PMID 28592311, 2017). "In previous models, reduced SIRT1 expression has been associated with impaired reverse cholesterol transport, increased atherosclerotic risk, and susceptibility to gallstone formation, whereas enhanced SIRT1 activity exerts protective effects against non-alcoholic fatty liver disease (NAFLD)." (PMID 41009597, 2025). "Among SIRTs, SIRT1 plays a pivotal role in cellular defense against oxidative stress and in modulating insulin sensitivity and β-cell function in the context of the pathophysiological network of nonalcoholic fatty liver disease and T2DM." (PMID 41234228, 2025). "In a previous study, miR-34a was shown to suppress SIRT1 in nonalcoholic fatty liver disease." (PMID 37107244, 2023). "Therefore, Sirt1 activation is important for reversing metabolic diseases, such as nonalcoholic fatty liver disease, with relevance to tendinopathy." (PMID 37545895, 2023). "SIRT1 plays an important biological role in regulating liver lipid metabolism, oxidative stress, and inflammation, and can be used as a therapeutic target for the treatment of alcoholic and non-alcoholic fatty liver diseases." (PMID 36968587, 2023). "Additionally, resveratrol alleviated nonalcoholic fatty liver disease primarily via AMPK/Sirt1 and anti-inflammatory signaling pathways." (PMID 37767399, 2023). "Several studies have shown that the inhibition of SIRT1 expression may result in the development of alcoholic as well as non-alcoholic fatty liver diseases." (PMID 30411173, 2019). "Moreover, increased hepatic miR-181a impaired glucose and lipid homeostasis by silencing sirtuin 1 in non-alcoholic fatty liver disease." (PMID 30717412, 2019). "However, the effects of RGZ on Sirt1 in in vitro and in vivo models of non-alcoholic fatty liver disease (NAFLD) and the synergistic effects of different sirtuin isoforms on metabolic regulation have not yet been reported." (PMID 25133775, 2014). "In nonalcoholic fatty liver disease, allyl isothiocyanate (AITC) ameliorates lipid accumulation and inflammation through the SIRT1/AMPK and NF-κB signaling pathways." (PMID 39372420, 2024). "SIRT1 has been shown to play a protective role against ALD and non-alcoholic fatty liver disease (NAFLD) by changing the acetylation status of target molecules to seemingly inhibit inflammation and steatosis." (PMID 28134813, 2017). "Moreover, activation of SIRT1 is protective against metabolic disorders known to affect patients with SBMA, such as nonalcoholic fatty liver disease, impaired glucose homeostasis, and mitochondrial dysfunction." (PMID 38452174, 2024). "Consequently, it has been described the participation of SIRT1, and other sirtuins, in some metabolic diseases, NAFLD (non-alcoholic fatty liver disease) among them, both in animal models and humans." (PMID 32485811, 2020). "In the liver, SIRT1 activity decreases de novo lipogenesis by suppressing the activity of the transcription factor SREBP-1c, while AMPK up-regulates free fatty acid oxidation via inhibition of acetyl-CoA carboxylase—effects that are useful for management of non-alcoholic fatty liver disease." (PMID 35216170, 2022).
colitis (69 papers, 2011 to 2026). Inflammation of the colon. "Using microbiota-depleted mice with or without fecal transplantation, we further demonstrate that Paneth cell SIRT1 deficiency ameliorates colitis by interacting with the gut microbiota." (PMID 41826553, 2026). "Specifically, the decrease in SIRT1 levels, inhibition of its activity, or generation of mutations that lower its activity have been linked to intestinal inflammation and colitis in human and rodent models." (PMID 40672369, 2025). "Intestinal SIRT1-deficient mice with defective gut microbiota exhibit more severe colitis than the control mice when induced by dextran sodium sulfate." (PMID 40713669, 2025). "This is consistent with the notion that SIRT1 activation is linked to the alleviation of colonic injury in experimental IBD models—including AA-induced colitis—culminating in improved colitis symptoms." (PMID 37111290, 2023). "Increasing evidence from human and rodent studies suggests that colitis, microbiota dysbiosis and intestinal barrier damage are closely associated with impairment of intestinal SirT1 signaling pathway." (PMID 36615829, 2022). "Our findings in the present study show that DSS-induced colitis causes a disturbance in hepatic lipid metabolism through the disruption of SIRT1-mediated metabolic processes including fatty acid oxidation, RCT, WAT browning, and BAT thermogenesis." (PMID 33674694, 2021). "SIRT1 also participates in the development of chronic spontaneous colitis in an IL-10-deficient mouse model." (PMID 34887866, 2021). "Colitis is also associated with reduction of Sirt1 expression and elevation of NF-κB activation; curcumin was shown to reverse them by promoting Sirt1 signaling activation." (PMID 34380504, 2021). "Intestinal epithelium-specific knockout of SIRT1 in aged mice induced spontaneous inflammation and tissue damage in the colon and increased their susceptibility to colitis." (PMID 33414704, 2020). "Induction of DSS-colitis associates with significant reduction of Sirt1 in both WT and Smad7 Tg mice, but this effect is more prominent in Smad7 Tg mice." (PMID 30147698, 2018). "Similar to this result, the mouse experimental model of dextran sodium sulfate-induced colitis was associated with a decrease in SIRT1 gene expression and resveratrol treatment significantly reversed the expression of SIRT1." (PMID 22357324, 2012). "SIRT1 deficiency in the intestinal epithelium leads to increased faecal bile acid levels, reduced Lactobacillus abundance, and heightened susceptibility to intestinal inflammation and colitis." (PMID 40136715, 2025). "In summary, we demonstrated that cZFP609 was highly expressed in the CSMCs of Sirt1-Tg mice, which may be associated with increased susceptibility to colitis via suppression of HIF-1α nuclear translocation." (PMID 40076434, 2025). "Notably, mice receiving a selective SIRT1 inhibitor with butyrate treatment displayed marked colitis, characterized by high Th17 cell levels and Th17-associated cytokine profile, providing evidence that butyrate therapeutic effect is SIRT1-dependent." (PMID 38591915, 2024). "Furthermore, Colitis was shown to be associated with a decrease in silent mating type information regulation-1 (Sirt1) and concomitantly with NF-κB." (PMID 34380504, 2021). "Res activates Sirt1 and then causes NF-κB down-regulation, which can eliminate colitis." (PMID 34944291, 2021). "SIRT1 deficiency may inhibit colitis development by inducing Tregs." (PMID 37483618, 2023). "Moreover, the adoptive transfer of TE cells from SIRT1-deficient mice into B6/Rag1-/-mice resulted in lower colitis disease activity and reduced weight loss, as well as a 2.8-fold increase in the formation of iTregs, compared with mice receiving wild-type T cells." (PMID 34887866, 2021). "SIRT1 was reported to protect against oxidative stress and plays an important role in protection against colitis." (PMID 40076434, 2025).